PEX10 (peroxisomal biogenesis factor 10)
Description:
E3 ubiquitin-protein ligase component of a retrotranslocation channel required for peroxisome organization by mediating export of the PEX5 receptor from peroxisomes to the cytosol, thereby promoting PEX5 recycling. The retrotranslocation channel is composed of PEX2, PEX10 and PEX12; each subunit contributing transmembrane segments that coassemble into an open channel that specifically allows the passage of PEX5 through the peroxisomal membrane (By similarity). PEX10 also regulates PEX5 recycling by acting as a E3 ubiquitin-protein ligase. When PEX5 recycling is compromised, PEX10 catalyzes polyubiquitination of PEX5 during its passage through the retrotranslocation channel, leading to its degradation (By similarity).
Synonyms: RNF69; NALD; PBD6A; PBD6B
Tractability: Antibody: UniProt predicts a signal peptide or a membrane-spanning region. PROTAC: ubiquitination databases record sites on it; its protein half-life has been measured.
Gene: Protein-coding gene on chromosome 1 (2,403,964 to 2,413,797, reverse strand). Ensembl gene ENSG00000157911.
Subcellular location: Peroxisome membrane
Pathways (Reactome):
Metabolism of proteins: E3 ubiquitin ligases ubiquitinate target proteins
Protein localization: Peroxisomal protein import
Gene Ontology:
Molecular function: protein binding; ubiquitin protein ligase activity; protein transmembrane transporter activity; zinc ion binding
Biological process: cellular response to reactive oxygen species; peroxisome organization; protein import into peroxisome matrix; protein import into peroxisome matrix, receptor recycling; protein polyubiquitination; proteasome-mediated ubiquitin-dependent protein catabolic process; protein import into peroxisome matrix, substrate release; protein quality control for misfolded or incompletely synthesized proteins; protein ubiquitination
Cellular component: peroxisomal membrane; peroxisome; ubiquitin ligase complex
Genetic constraint (gnomAD): Loss-of-function variants: 32 observed, 34.83 expected, observed/expected ratio (o/e) 0.92, 90% interval 0.69 to 1.23. The upper end of that interval is the gene's LOEUF score, 1.23, which puts it in group 5 of 6, group 1 being the genes least tolerant of losing a copy. Missense variants: 483 observed, 432.95 expected, observed/expected ratio (o/e) 1.12, 90% interval 1.03 to 1.2. Synonymous variants: 206 observed, 194.07 expected, observed/expected ratio (o/e) 1.06, 90% interval 0.95 to 1.19.
Gene-disease validity (ClinGen):
ClinGen rates the evidence that PEX10 causes each of these diseases.
peroxisome biogenesis disorder (autosomal recessive): Definitive.
Homologues: Orthologues: chimpanzee PEX10 (98% identical), macaque PEX10 (90% identical), rat Pex10 (84% identical), mouse Pex10 (82% identical), guinea pig PEX10 (80% identical), dog PEX10 (78% identical), tropical clawed frog pex10 (54% identical), zebrafish pex10 (53% identical), Drosophila melanogaster Pex10 (29% identical), Caenorhabditis elegans C32D5.11 (26% identical).
Diseases named in the same sentence as PEX10 in open-access papers:
PEX10 is named in the same sentence as 29 diseases in open-access papers, as found by Europe PMC text mining. Sharing a sentence is not in itself a finding about the gene and the disease. The quoted sentences say what the papers report.
Zellweger syndrome (6 papers, 2013 to 2025). "We report a case of a patient with Zellweger spectrum disorder due to a novel mutation in the PEX10 gene, presenting with a mild late-onset neurological phenotype." (PMID 28784167, 2017). "The majority of the reported patients with mutations in PEX10 belong to the severe Zellweger syndrome or neonatal adrenoleukodystrophy, but also milder clinical forms with mutations in PEX10 have been described." (PMID 28784167, 2017). "Loss-of-function mutations in PEX10 are one cause of Zellweger syndrome, a severe neurological disorder characterized by brain findings of centrosylvian PMG, medial pachygyria, subcortical heterotopias, and simplified inferior olivary nuclei." (PMID 24252393, 2013). "The phenotype spectrum of the PEX10-related PBDs ranges from lethal to mild, and the clinical diagnosis include Zellweger syndrome, NALD, and IRD based on the onset age, symptoms, and signs." (PMID 40267090, 2025). "Approximately 80% of PBD patients are classifiedin the Zellweger syndrome spectrum, which is generally caused by mutations in the PEX1, PEX6, PEX10, PEX12, or PEX26 genes." (PMID 33912394, 2021). "Zellweger spectrum disorders (ZSDs), including archetypal Zellweger syndrome, neonatal adrenoleukodystrophy (NALD) and infantile Refsum disease (IRD), are PBDs caused by mutations in peroxin genes (PEX1, PEX2, PEX3, PEX5, PEX6, PEX10, PEX11β, PEX12, PEX13, PEX14, PEX16, PEX19 or PEX26)." (PMID 40949164, 2025). "However, Zellweger syndrome is a recessive disorder, and deletion of one PEX10 allele would not account for brain malformations on its own." (PMID 24252393, 2013).
peroxisome biogenesis disorder (4 papers, 2016 to 2025). "The connected component of peroxisomal disorders expressed in the hypothalamus consists of PEX19, PEX10, PEX6, and PEX7." (PMID 27748412, 2016).
cerebellar ataxia (3 papers, 2011 to 2025). A neurological syndrome characterized by clumsy and uncoordinated movement of the limbs, trunk, and cranial muscles. "Five patients described with mild clinical presentation caused by PEX10 variants all show cerebellar ataxia, suggesting PBD to be considered in the differential diagnosis of autosomal recessive ataxia." (PMID 28784167, 2017). "While this work was in progress, PBD patients with mild phenotypes including cerebellar ataxia were shown to have mutations in PEX10 gene or PEX16 gene." (PMID 21392394, 2011).
male infertility (2 papers, 2020 to 2023). The inability of the male to effect fertilization of an ovum after a specified period of unprotected intercourse. "The gene is highly expressed in testis, and a meta-analysis suggests that PEX10 polymorphisms are associated with male infertility, especially with non-obstructive azoospermia susceptibility." (PMID 33276343, 2020).
axonal motor neuropathy (1 paper, 2011). "However, these patients displayed additional neurological symptoms including axonal motor neuropathy and decreased vibration sense in PEX10- mutated patients and spastic paraparesia, leukodystrophy peripheral neuropathy and cataracts in patients with PEX16 mutation." (PMID 21392394, 2011).
depression (1 paper, 2023). "While only one CpG in PEX10 appeared to positively correlate between blood and brain, our results nevertheless suggest DNAm at birth as a potential molecular biomarker of later neurodevelopmental trajectories in children prenatally exposed to (es)citalopram and depression." (PMID 37147306, 2023).
dyslipidemia (1 paper, 2022). "Therefore, this study suggests that the mechanism of JTTZR intervention in obese T2DM with dyslipidemia may be related to the upregulation of PEX10, which enhances peroxisome biosynthesis." (PMID 35957821, 2022).
peroxisome biogenesis disorder 6B (1 paper, 2015). "The variant of His290 of peroxisome biogenesis factor 10 (PEX10) has been related to peroxisome biogenesis disorder 6B disease." (PMID 26549015, 2015).
prostate carcinoma (1 paper, 2024). A carcinoma that arises from epithelial cells of the prostate gland. "This suggests that the increased level of senescence caused by knocking down PEX10 in prostate cancer cells is mediated through elevated ROS levels." (PMID 39097593, 2024). "Interestingly, data from the Cancer Genome Atlas (TCGA) shows that PEX10 expression is markedly elevated in prostate cancer and closely associated with lymph node metastasis of prostate cancer." (PMID 39097593, 2024). "The extent of PEX10’s involvement in peroxisomal function within the context of prostate cancer and its influence on ROS levels remains ambiguous." (PMID 39097593, 2024). "In summary, our study demonstrates a previously unrecognized function of AR inhibiting ROS accumulation by upregulating PEX10 and suggests a new strategy of using enzalutamide in prostate cancer treatment." (PMID 39097593, 2024). "Here, we confirmed PEX10 can be induced by ROS activators while reduce ROS level in prostate cancer cells, which weakened the anti-tumor effect of ROS activators." (PMID 39097593, 2024). "As delineated in this study, PEX10 appears to exert an influence on the trajectory of prostate cancer by instigating oxidative stress, ferroptosis, and cellular senescence." (PMID 39097593, 2024). "To further demonstrate that the ROS generated by knocking down PEX10 can promote senescence in prostate cancer cells, we conducted additional experiments." (PMID 39097593, 2024). "In contrast, enzalutamide inhibits PEX10 expression and eventually increase ROS anti-tumor function in prostate cancer." (PMID 39097593, 2024). "This study reveals a previously unrecognized function of enzalutamide and AR by regulating PEX10 and suggests a new strategy of enzalutamide application in prostate cancer treatment." (PMID 39097593, 2024). "The incorporation of ML210 and the overexpression of PEX10 in prostate cancer provide additional substantiation for this observation." (PMID 39097593, 2024). "To further investigate the role of PEX10 in ferroptosis and prostate cancer proliferation, we downregulated PEX10 in both LNCaP and C4-2 cells." (PMID 39097593, 2024). "The IC50 results indicate that reducing PEX10 increases the sensitivity of prostate cancer to enzalutamide." (PMID 39097593, 2024). "Our research indicates that in prostate cancer, the heightened expression of AR achieves this goal by facilitating the expression of PEX10, a process that can be suppressed by enzalutamide." (PMID 39097593, 2024). "Consistent with the previous results, both colony formation and CCK8 assay affirm that the overexpression of PEX10 in various prostate cancer cells markedly enhances cell proliferation, suggesting that PEX10 plays a role in promoting cell proliferation in prostate cancer." (PMID 39097593, 2024). ", which suggest that PEX10 may also involve in the cellular senescence induced by ROS in prostate cancer cells." (PMID 39097593, 2024). "Dihydrotestosterone (DHT) treatment significantly increased PEX10 expression at the mRNA and protein levels in prostate cancer cells, including C4-2 and LNCaP cells, while enzalutamide treatment decreased PEX10 expression, which is consistent with the changes in KLK3 and our previous conclusions." (PMID 39097593, 2024). "Additionally, we found that overexpression of PEX10 reduces lipid peroxidation and ferroptosis in prostate cancer." (PMID 39097593, 2024). "Our results suggest that ML210 promote PEX10 expression and lead to the elimination of ROS in prostate cancer, while enzalutamide could inhibit PEX10 function and synergy with ML210 to exert a better anti-tumor effect." (PMID 39097593, 2024). "Importantly, in the absence of PEX10, DHT no longer decreased H2O2 levels, confirming that enzalutamide could mitigate ROS in prostate cancer by inhibiting PEX10." (PMID 39097593, 2024).
prostate carcinoma (continued). "In addition, as a downstream gene of the AR, PEX10 may involve in the ROS depletion, ferroptosis sensitivity and cellular senescence of prostate cancer and promote prostate cancer cell proliferation." (PMID 39097593, 2024). "Firstly, following PEX10 knockdown, we supplemented with the ROS inhibitor NAC and observed a significant reduction in ROS levels produced by PEX10 knockdown in prostate cancer cells." (PMID 39097593, 2024).
tumor (5 papers, 2021 to 2025). "Many genes involved in peroxisome formation, including PEX10, play important roles in maintaining ferroptosis sensitivity in various tumor cells." (PMID 39097593, 2024). "The anti-tumor drug enzalutamide inhibits PEX10 by inhibiting the function of AR, and synergize with ROS activators ML210 or RSL3 to produce a stronger anti-tumor effect, thereby sensitizing cells to ROS activators." (PMID 39097593, 2024). "Contrarily, PEX10 overexpression partially abolished the tumor cell inhibitory effects of both ML210 and enzalutamide." (PMID 39097593, 2024). "In contrast, analysis for mRNAs encoding for peroxisomal biogenesis proteins (Pex7, Pex10, Pex12), and proteins for peroxisomal proliferation (Pex11α, Pex11β) were significantly upregulated in PMA tumor compared to control tissue." (PMID 34360635, 2021). "In the previous results, we confirmed that enzalutamide combined with ML210 can achieve a better inhibitory effect on tumor cell proliferation, and PEX10 may play an important role in this process." (PMID 39097593, 2024). "Furthermore, corroborating evidence from both CCK8 and colony formation assays affirmed that the combination of ML210 and PEX10 knockdown achieved superior inhibition of tumor cell growth compared to ML210 or PEX10 knockdown alone." (PMID 39097593, 2024). "Results showed ML210 and enzalutamide combination administration could significantly inhibit the tumor growth, and both the xenograft size and tumor growth rate significantly increased after PEX10 overexpression." (PMID 39097593, 2024). "Conversely, the suppression of PEX10 could amplify the anti-tumor impact of ML210." (PMID 39097593, 2024).
infection (2 papers, 2015 to 2023). The state of being infected such as from the introduction of a foreign agent such as serum, vaccine, antigenic substance or organism. "After 8 days of infection, the loss of pex5, pex10, or pex33 severely reduced the fungal burden in the lungs as determined by the recovery of CFUs." (PMID 37432032, 2023).
neoplastic disorders (1 paper, 2025). "PEX2 and other peroxins—namely, PEX5, PEX10, and PEX12—play a pivotal role in ensuring the survival of malignant cells and, consequently, emerge as prospective therapeutic targets for combating neoplastic disorders." (PMID 40487257, 2025).
PEX10 also shares sentences with these, for which no sentence is quoted: infantile Refsum disease (2 papers); achondroplasia (1); Ataxia (1); Azoospermia (1); brain malformations (1); Breast Invasive Carcinoma (1); breast tumour (1); cataract (1); clear-cell renal cell carcinoma (1); Dextrocardia (1); Dystonia (1); Intellectual disability (1); leukodystrophy (1); neurodevelopmental disorder (1); neurological disorder (1); ovarian carcinoma (1); Seckel syndrome (1).